RARB (retinoic acid receptor beta)
Diseases named in the same sentence as RARB in open-access papers (continued):
Sharing a sentence is not in itself a finding about the gene and the disease.
vitamin A deficiency (3 papers, 2008 to 2015). Deficiency of vitamin A due to malnutrition, malabsorption, or dietary lack. "Vitamin A deficiency preferentially decreases hepatic RARB expression, and regulates hepatic glucose metabolic enzymes." (PMID 18254975, 2008). "Findings from this study suggest that cigarette smoke-induced lung retinoic acid depletion may involve two independent pathways, RARα- and RARβ-mediated, responsible for the increased cancer risk associated with cigarette smoke-induced vitamin A deficiency." (PMID 26462767, 2015). "Additionally, vitamin A deficiency is linked with an increased expression of RARα, in contrast with the decreased expression of RARβ." (PMID 26462767, 2015).
adenoma (2 papers, 2010 to 2014). A neoplasm arising from the epithelium. "ESR1 has been shown to occur in histologically normal colon epithelium in an age dependent fashion, CDH13 is also frequently methylated in CRC and seems to be correlated with the adenoma-carcinoma transition, like other genes with methylation frequencies > 30% (CDKN2B, RASSF1, RARB, APC and TIMP3)." (PMID 25091577, 2014).
Alzheimer disease (2 papers, 2016 to 2025). A progressive, neurodegenerative disease characterized by loss of function and death of nerve cells in several areas of the brain leading to loss of cognitive function such as memory and language. "LE135, the selective RARβ antagonist used in the present study, decreases RA’s neuroprotective effects in studies of Alzheimer’s disease." (PMID 27611191, 2016).
Anxiety (2 papers, 2022 to 2025). Intense feelings of nervousness, tension, or panic often arise in response to interpersonal stresses. "For example, the RARB:RXRG dimer’s activities in amygdala have been linked to expression of anxiety-related phenotypes, and RORA is associated with enhanced fear response in humans and mice." (PMID 35192674, 2022).
asthma (2 papers, 2018 to 2023). "In a previous study, we have showed that HHIP, FAM13A1, AGER and RARB associated with pre-bronchodilator lung function in subjects with asthma." (PMID 30068317, 2018).
autism spectrum disorder (2 papers, 2020 to 2023). A spectrum of developmental disorders that includes autism, and Asperger syndrome. "Disruptions to RARB lead to neurodevelopmental delay and are associated with autism spectrum disorder." (PMID 37730546, 2023).
developmental delay (2 papers, 2022 to 2024). "Patient 1, who has chorioretinal coloboma, iris coloboma, optic nerve coloboma, dystonia, spastic diplegia, global developmental delay, and dysmorphic facial features has a de novo likely pathogenic variant in the RARB gene reported during exome reanalysis." (PMID 35937981, 2022). "In this study, we report the first noncoding variant in RARB, c.157+1895G>A, associated with a complex developmental ocular phenotype accompanied by significant global developmental delay, both consistent with previously reported features of MCOPS12 associated with RARB pathogenic variants." (PMID 39450403, 2024).
endometrial cancer (2 papers, 2019 to 2025). Primary or metastatic malignant neoplasm involving the endometrium (mucous membrane that lines the endometrial cavity). "RARβ hypermethylation has been found in 92% of endometrial cancers and 75% of endometrial hyperplasias." (PMID 30944670, 2019). "Similarly, we observed significantly elevated nuclear expressions of RARβ in progestin-resistant endometrial cancer and hyperplasia tissues, particularly in progestin-resistant endometrial hyperplasia patients." (PMID 40371351, 2025).
endometriosis (2 papers, 2015 to 2024). The growth of functional endometrial tissue in anatomic sites outside the uterine body. "Additional defects in H3K27ac deposition in individuals with endometriosis were observed in the well-known progesterone-responsive genes RARB and CEBPA loci." (PMID 38402336, 2024). "Retinoic acid receptor beta (RARB) was decreased on days 2 and 4 of EPC treatment in endometriosis relative to normal." (PMID 38402336, 2024).
Fibroadenoma (2 papers, 2011 to 2015). A benign tumor of the breast characterized by the presence of stromal and epithelial elements. "Expression of both RARα and RARβ were highest in fibroadenoma tissue." (PMID 21283523, 2011). "Total RNA extracted from malignant (n = 75), normal (n = 15), and fibroadenoma (n = 10) breast tissue biopsies was analysed using RQ-PCR targeting NIS, RARα, RARβ, ERα, PI3K, THRα and THRβ." (PMID 21283523, 2011). "It is interesting to note that the 3 genes in this study found to be differentially expressed in fibroadenoma and malignant tissue (NIS, RARβ and THRβ), have all been suggested to have tumour suppressor roles." (PMID 21283523, 2011). "Human breast tissue specimens (malignant n = 75, normal n = 15, fibroadenoma n = 10) were analysed by RQ-PCR targeting NIS, receptors for retinoic acid (RARα, RARβ), oestrogen (ERα), thyroid hormones (THRα, THRβ), and also phosphoinositide-3-kinase (PI3K)." (PMID 21283523, 2011).
glaucoma (2 papers, 2011 to 2024). Increased pressure in the eyeball due to obstruction of the outflow of aqueous humor. "Increased FOXC1 expression due to gene duplication has been shown to result in anterior segment defects, including iris hypoplasia with glaucoma, microcornea, and Peters anomaly, similar to the ocular features described here in the individual with a de novo RARB c.157+1895G>A variant." (PMID 39450403, 2024).
glioma (2 papers, 2015 to 2020). A benign or malignant brain and spinal cord tumor that arises from glial cells (astrocytes, oligodendrocytes, ependymal cells). "ccfDNAs in glioma were associated with differential methylation levels of MGMT, cyclin-dependent kinase inhibitor 2A, multiple tumor suppressor 1 p16/(INK4a), p73, and retinoic acid receptor beta (RARb)." (PMID 32849827, 2020).
Hepatic steatosis (2 papers, 2021 to 2023). Steatosis is a term used to denote lipid accumulation within hepatocytes. "Here we demonstrated that hepatocyte loss of one of the effectors of retinoid signaling, RARβ, is associated with a greater ETOH-induced level of hepatic steatosis and oxidative stress." (PMID 37569418, 2023). "To elucidate whether AC261066, a selective RARβ2 agonist, limits liver steatosis via RARβ in hepatocytes, we examined AC261066’s effects on lipid accumulation in parental and RARβ knockout (RARβ KO) HepG2 cells generated using CRISPR/Cas9 technology." (PMID 34688661, 2021). "In both models, treatment of WT mice with a selective RARβ2 agonist (with RARβ2 being the most abundant RARβ isotype), AC261066, limited hepatic steatosis, cellular stress, and inflammation compared to mice not given AC261066." (PMID 37569418, 2023).
Intellectual disability (2 papers, 2020 to 2021). "RARB is biologically constrained by natural selection; extreme phenotypes attributed to rare exonic variants in this gene include intellectual disability, spasticity and congenital ocular defects." (PMID 30532020, 2020). "Also, mutations in the retinoic acid receptor beta gene, RARB, lead to intellectual disability with progressive motor impairment." (PMID 34848785, 2021).
invasive breast carcinoma (2 papers, 2014). A carcinoma that infiltrates the breast parenchyma. "Loss of RARβ gene expression has been reported in ∽50% of invasive breast carcinomas and it has been proposed as an essential player in the conversion of non-invasive breast cancer into invasive disease." (PMID 24720764, 2014).
liver disease (2 papers, 2023 to 2024). "Collectively, our data on RARβ and previous research by others on RARα indicate that RARs are protective against steatosis and could be exploited therapeutically to limit the onset of liver disorders characterized by a dysregulation of lipid metabolism." (PMID 37569418, 2023). "The nuclear retinoic acid receptors RARβ and RXRα were downregulated in the TGF-β groups in correspondence with previous studies on human liver disease patients." (PMID 39044210, 2024).
lung diseases (2 papers, 2013 to 2025). "Beyond its implications in lung diseases, RARB’s abnormal expression has also been implicated in the development of various diseases, including certain cancers." (PMID 39723714, 2025). "pointed out the sensitivity of non-small cell lung cancer (NSCLC) cells to demethylation drugs and retinoic acid, which further confirmed the importance of RARB in lung diseases." (PMID 39723714, 2025). "A panel of 4 genes (MYF6, SIX6, BCL2 and RARB) was able to diagnose stage I NSCLC from non-cancerous lung diseases with a sensitivity of 93.07% and a specificity of 86.67%." (PMID 23599765, 2013). "The methylation frequencies (29.70–64.36%) of 7 genes (MYF6, SIX6, SOX1, RARB, BCL2, PHOX2A and FOLX2) in stage I NSCLC were significantly higher compared with those in non-cancerous lung disease controls (P<0.05)." (PMID 23599765, 2013). "The methyaltion frequencies of 7 genes: MYF6, SIX6, SOX1, RARB, BCL2, PHOX2A and FOLX2 were significantly higher in stage I NSCLC than in non-cancerous lung diseases." (PMID 23599765, 2013). "This study showed that 7 genes (MYF6, SIX6, SOX1, RARB, BCL2, PHOX2A and FOLX2) were frequently methylated in 101 cases of patients with stage I NSCLC, while rarely methylated in 30 patients with non-cancerous lung diseases." (PMID 23599765, 2013).
metastatic disease (2 papers, 2003 to 2024). "The high levels of RARα, RARβ and RXRα determined in our tumor tissues associated with unfavorable clinical factors such as relapsed and “de novo” metastatic disease." (PMID 39323992, 2024).
myopia (2 papers, 2010 to 2013). "The purpose of this study was to determine if high myopia is associated with single nucleotide polymorphism (SNP) variants in the retinoic acid receptor beta (RARβ) gene in Chinese subjects." (PMID 20508731, 2010). "Guinea pigs with experimental myopia display elevated levels of RA and RARβ in the retina, and there appears to be positive feedback between increased RA and elevated RARβ." (PMID 23946634, 2013). "Five variations in RARβ were detected in Chinese subjects with high myopia, including 32574G>A, 32629G>A, 32645C>T, 32647T>G, and 151973C>T, of which only 32647T>G (NCBI notes as rs58244688 and rs2067964) had already been reported." (PMID 20508731, 2010). "Two of the SNPs were located in the coding regions of RARβ, and the distribution of one of these in the high myopia group, 32574G>A, was different from that predicted by the Hardy–Weinberg equilibrium." (PMID 20508731, 2010). "Given the critical role that RA plays in scleral remodeling and the development of myopia, it is likely RA receptors, including RARβ, are important in mediating these changes." (PMID 20508731, 2010). "Five SNP variants in RARβ were detected in Chinese subjects with high myopia, none of them were associated significantly with high myopia." (PMID 20508731, 2010).
osteosarcoma (2 papers, 2023 to 2025). A usually aggressive malignant bone-forming mesenchymal neoplasm, predominantly affecting adolescents and young adults. "RARB has previously been identified in gene regulatory network of osteosarcoma, whereas FOXC1 (together with FOXC2) was shown to direct hypertrophic chondrocyte maturation and function toward primary ossification center formation and osteoblast recruitment." (PMID 40225119, 2025). "The signals of the other two MAPK proteins, phosphorylated p38 and JNK, were relatively weak in osteosarcoma cells, despite a subtle increase after RARb antagonist treatment." (PMID 36681687, 2023). "We demonstrated that specific blockade of RARb can significantly reduce the growth of all the osteosarcoma cell lines, indicating that RARb may be one of the primary targets by which BMS493 inhibits the growth of osteosarcoma cells." (PMID 36681687, 2023). "Together, our results revealed that modulators of RARb, PPARg, LXRs and Rev-Erba inhibit osteosarcoma growth both in vitro and in vivo through the mTOR signaling pathway, suggesting that treatment with these NR modulators is a novel potential therapeutic strategy." (PMID 36681687, 2023). "The immunofluorescence and western blotting results showed that the RARb antagonist LE135, PPARg antagonist T0070907, LXR agonist T0901317 and Rev-Erba agonist SR9011 reduced the KI-67 and PCNA protein levels in all three osteosarcoma cell lines." (PMID 36681687, 2023). "In conclusion, our study revealed that four NR modulators, namely, the RARb antagonist LE135, PPARg antagonist T0070907, LXR agonist T0901317 and Rev-Erba agonist SR9011, effectively inhibit the growth of osteosarcoma in vitro and in vivo." (PMID 36681687, 2023). "In addition to RARa, RARb and RARg are also thought to be activated by ATRA in osteosarcoma cells." (PMID 36681687, 2023). "The inhibitory effects of the RARb antagonist LE135, PPARg antagonist T0070907, LXR agonist T0901317 and Rev-Erba agonist SR9011 were all abolished in the corresponding NR-knockout cells, indicating that the NR modulators specifically target the corresponding NRs to inhibit osteosarcoma cell growth." (PMID 36681687, 2023). "We found that chemical inhibition of RARb and PPARg (LE135 and T0070907) and activation of LXRs and Rev-Erba (T0901317 and SR9011) significantly suppressed osteosarcoma cell proliferation but not osteoblast proliferation." (PMID 36681687, 2023). "Four chemicals, namely, the RARb antagonist LE135, PPARg antagonist T0070907, LXR agonist T0901317 and Rev-Erba agonist SR9011, can inhibit the growth of all three osteosarcoma cell lines without affecting the growth of normal osteoblasts." (PMID 36681687, 2023). "Our results suggested that 4 NR modulators, namely, the RARb antagonist LE135, PPARg antagonist T0070907, LXR agonist T0901317 and Rev-Erba agonist SR9011, can significantly suppress osteosarcoma cell growth without exerting toxic effects on normal osteoblast cells." (PMID 36681687, 2023).
pancreatic ductal adenocarcinoma (2 papers, 2023). An infiltrating adenocarcinoma that arises from the epithelial cells of the pancreas. "Intriguingly, downregulation of the expression of RARα and RARβ has been reported in pancreatic ductal adenocarcinoma and associated with better overall survival." (PMID 37569466, 2023). "Real-time RT-PCR examination of the expression of RARs revealed downregulation of RARα, RARβ, RXRα, and RXRβ in pancreatic ductal adenocarcinoma tissue." (PMID 37569466, 2023).
Papillary thyroid cancer (2 papers, 2013 to 2016). "The aim of this study was to determine the role of miR-146 family in inhibition of the RARB gene in papillary thyroid carcinoma." (PMID 27011326, 2016). "However, expression of RARβ is lowered in papillary thyroid carcinoma (PTC), contributing to promotion of tumor growth and inefficiency of retinoic acid and radioactive iodine treatment." (PMID 27011326, 2016). "Our study is the first to show the regulation of RARB by microRNA, and indicates that understanding of this interaction might provide a new insight into the molecular mechanisms leading to development of papillary thyroid carcinoma." (PMID 27011326, 2016).
psoriasis (2 papers, 2008 to 2023). An autoimmune condition characterized by red, well-delineated plaques with silvery scales that are usually on the extensor surfaces and scalp. "Psoriasis, a skin disease has been successfully treated with Tazarotene, a retinoid with selective activity towards RARβ and RARγ, indicating a specific role for RARγ and/or RARβ in the disease." (PMID 18398471, 2008).
steatosis (2 papers, 2021 to 2023). Increased lipid within the cytoplasm of cells. "Thus, our current data reported here underscores the role of RARβ in limiting steatosis in two different models, one caused by high fat intake, and one by ETOH." (PMID 37569418, 2023). "The BKO mice fed the pair-fed (PF) liquid diet also showed increased triglyceride levels compared to the WT mice on the same diet, indicating that RARβ-deficient hepatocytes are more susceptible to steatosis both with and without ETOH." (PMID 37569418, 2023). "The increased steatosis observed in the livers of the BKO mice after ETOH treatment is consistent with our recently published data indicating that RARβ-KO HepG2 cells treated with oleate and palmitate show dramatic increases in the numbers of lipid droplets compared to HepG2 parental cells." (PMID 37569418, 2023). "Importantly, we provided direct evidence that AC261066 attenuates HFD-induced steatosis in hepatocytes via RARβ." (PMID 34688661, 2021). "We do not know whether RARβ limits steatosis by repressing specific genes in hepatocytes in the absence of the endogenous agonist RA, or if RA is required for either transcriptional activation or repression for RARβ to limit steatosis." (PMID 37569418, 2023).
teratocarcinoma (2 papers, 2007 to 2013). A germ cell tumor characterized by the presence of an embryonal carcinoma component and a teratoma component. "In cultured F9 teratocarcinoma stem cells, OA was shown to induce differentiation through the regulation of differentiation-specific genes, including laminin B1, type IV collagen and RARβ." (PMID 24137431, 2013).
/T-cell lymphoma (1 paper, 2011). "Various tumour suppressor genes have been shown to be frequently hypermethylated in NK/T-cell lymphoma including p73, CDKN2A, CDKN2B, hMLH1 and RARβ, but hypermethylation of miR-124-1 is one of the first reports of methylation of miR in NK/T-cell lymphoma." (PMID 21544199, 2011).
Adenomatous Polyposis Coli (1 paper, 2019). "Compared with adjacent normal tissues, tumor samples exhibited hypermethylation of Estrogen Receptor 1, Cadherin 13, Retinoic Acid Receptor Beta, Cell Surface Adhesion Molecule, and Adenomatous Polyposis Coli (ESR1, CDH13, RARB, IGSF4, and APC) genes." (PMID 31390840, 2019).
adenosquamous carcinoma (1 paper, 2013). A carcinoma composed of malignant glandular cells and malignant squamous cells. "The co-methylation of SIX6 and SOX1, or the co-methyaltion of SIX6, RARB and SOX1 was associated with adenosquamous carcinoma (ADC), and the co-methylation of BCL2, RARB and SIX6 was associated with smoking." (PMID 23599765, 2013).
adenovirus infection (1 paper, 2020). "During human adenovirus infection, the RARβ mRNA and protein levels were downregulated, but the overexpression of RARβ decreased human adenovirus production." (PMID 32867365, 2020). "Therefore, RARβ may have therapeutic effects for adenovirus infection, although the autophagy-mediated suppression of infection is unclear in RARβ-induced antiviral and anticancer effects." (PMID 32867365, 2020).
adrenal hypoplasia (1 paper, 2015). "Included in this group were AR, Coup-TFα, Coup-TFβ, dosage-sensitive sex reversal-adrenal hypoplasia congenital critical region on the X chromosome, gene 1 (DAX1), ERα, ERRα, HNF4γ, liver receptor homolog-1 (LRH1), NOR1, NURR1, PPARγ, RARβ, RORα, RORβ, and VDR." (PMID 26244663, 2015).